AGRN (agrin)
Diseases named in the same sentence as AGRN in open-access papers (continued):
Sharing a sentence is not in itself a finding about the gene and the disease.
glioblastoma (12 papers, 2012 to 2024). The most malignant astrocytic tumor (WHO grade IV). "Furthermore, in glioblastoma, agrin is degraded by MMPs which causes a dramatic effect on the distribution of aquaporin-4 (AQP4)." (PMID 22984437, 2012). "Agrin is necessary for polarized distribution, and its reduction causes the redistribution of AQP4 in human glioblastoma." (PMID 36672558, 2022). "Agrin is a large extracellular heparan sulfate proteoglycan and a normal component of the basal lamina of brain vessels; in glioblastoma, agrin content was found to be partially lost from the brain vasculature and replaced by tenascin." (PMID 34070023, 2021). "This role of agrin was first described in human glioblastoma samples and was further addressed in a mouse model, where differences in the appearance of OAPs were demonstrated between wild-type and agrin-devoid mice." (PMID 33297299, 2020). "In human glioblastoma, orthogonal arrays of particles (OAPs) are redistributed to membrane domains because of the degradation of the proteoglycan agrin by the increased activity of matrix metalloprotease 3 (MMP3)." (PMID 27517922, 2016). "Agrin is, on the other hand, an extracellular heparin sulphate proteoglycan and is previously shown to be downregulated in glioblastoma." (PMID 22262958, 2012). "For example, in human glioblastomas, the expression of α-dystroglycan is strongly reduced and may coincide with decreased expression of agrin and increased expression of matrix metalloproteinases 3 and 2/9." (PMID 33297299, 2020). "Agrin binds with AQP4 and leads to a strong immunoreactivity distribution in tumor tissues such as astrocytomas or glioblastomas, so that it may facilitate infiltration into the brain parenchyma, whereas it is restricted to the perivascular endfeet in normal brain." (PMID 27517922, 2016). "In addition, the activity of matrixmetalloproteinases MMP2, 9, and 3 play a pivotal role in this scenario: if agrin is cleaved by MMP3 —such as in glioblastoma—no typical OAPs are found and if MMP2 and 9 cleave dystroglycan —such as in glioblastoma—no OAPs are formed as well." (PMID 27483250, 2016). "Agrin is a substrate of MMP3, dystroglycan of MMP2 and 9, possibly the reason for the absence of agrin and dystroglycan around vessels in glioblastomas." (PMID 26115524, 2015).
myasthenia gravis (11 papers, 2014 to 2023). Myasthenia gravis (MG) is a rare, clinically heterogeneous, autoimmune disorder of the neuromuscular junction characterized by fatigable weakness of voluntary muscles. "Moreover, autoantibodies to Agrin, Lrp4, or MuSK cause myasthenia gravis (MG), which is likewise distinct from ALS." (PMID 29460776, 2018). "Myasthenia gravis (MG) is an acquired autoimmune disorder caused by autoantibodies binding acetylcholine receptors (AChR), muscle‐specific kinase (MuSK), agrin or low‐density lipoprotein receptor‐related protein 4 (Lrp4)." (PMID 34228850, 2021). "The engineered agrin was reported to attenuate the severity of experimental autoimmune myasthenia gravis." (PMID 32547365, 2020). "Myasthenia gravis (MG) is a chronic autoimmune disorder of the neuromuscular junction characterized by autoantibodies against acetylcholine receptors (AChR-Ab), muscle-specific kinase (MuSK-Ab), lipoprotein-related protein 4, or agrin in the postsynaptic membrane at the neuromuscular junction." (PMID 35645352, 2022). "This study aimed to establish a cell-based assay (CBA) for the detection of agrin antibodies (Agrin-Ab) to explore the clinical features of agrin antibody-positive Chinese patients with myasthenia gravis (Agrin-MG)." (PMID 34956185, 2021). "Administration of NT−1654, a C−terminal fragment of the neuron−specific agrin isoform, promoted the clustering of AChRs at NMJs and ameliorated muscle atrophy in model mice of SMA, CMS, and myasthenia gravis." (PMID 37108583, 2023). "LRP4 autoantibodies are detected in some patients with myasthenia gravis (MG), and the inhibition of the LRP4-agrin interaction appears to be responsible, at least in part, for their pathogenicity." (PMID 34849350, 2021).
myocardial infarction (11 papers, 2017 to 2025). Gross necrosis of the myocardium, as a result of interruption of the blood supply to the area, as in coronary thrombosis. "Despite the limited ability of adult myocardium to regenerate, AGRN has shown potential in stimulating the proliferation and repair of adult cardiomyocytes after a heart attack." (PMID 40299352, 2025). "A single administration of Agrin promotes cardiac regeneration in adult mice after myocardial infarction." (PMID 39548113, 2024). "Short-term myocardial infarction experiments, along with complementary murine studies, revealed that Agrin’s mechanisms of action include myocardial protection, improved angiogenesis, inflammatory suppression, and cell cycle reentry." (PMID 39548113, 2024). "In a model of myocardial infarction, adult mice treated with recombinant agrin showed cardiomyocyte proliferation, a reduction in scarring, and improved cardiac function at 35 days post infarction." (PMID 33718383, 2021). "This has been attributed to agrin, a heparan sulfate proteoglycan particularly abundant at P1, which promotes CM proliferation in vitro and is able to reactivate the CM proliferation in adult mice and pigs after myocardial infarction (MI)." (PMID 36555424, 2022). "Both in mouse and porcine models of myocardial infarction (MI), recombinant agrin injected locally in the damaged heart seems to have an overall cardioprotective effect, with anti-inflammatory and angiogenic components to add to CM protection and (mild) proliferation induction." (PMID 32612983, 2020). "In addition, one of the targets of MMP9, agrin, was more highly expressed at P1, compared with P7, and injection of agrin promoted cardiac regeneration in adult mice post-myocardial infarction." (PMID 31434209, 2019). "Agrin activates the ERK signaling pathway via the regulation of Fgf signaling and agrin protein injection in adult mice, following myocardial infarction, has been shown to promote heart regeneration in an ERK-dependent mechanism." (PMID 37174727, 2023). "The extracellular matrix protein agrin promotes cardiac regeneration in neonatal mice, and the potential benefit of local administration of agrin by retrograde delivery in coronary arteries after myocardial infarction (MI) was tested in three-month-old pigs." (PMID 35448069, 2022). "Agrin promotes cardiomyocyte proliferation in post-myocardial infarction hearts through DAG1 and YAP and in our study we observed a requirement for agrin to ensure YAP activation in the context of epicardial EMT." (PMID 33969874, 2021). "In addition, agrin activates the ERK signaling pathway via the regulation of Fgf signaling and agrin protein injection in adult mice, following myocardial infarction, and has been shown to promote heart regeneration in an ERK-dependent mechanism." (PMID 37174727, 2023). "Interestingly, agrin application led to increased nuclearization of YAP in cardiomyocytes 1 day after myocardial infarction and the inhibition of YAP prevented agrin-induced cardiomyocyte proliferation." (PMID 33718383, 2021).
muscular dystrophy (8 papers, 2012 to 2026). Muscular dystrophy (MD) refers to a group of more than 30 genetic diseases characterized by progressive weakness and degeneration of the skeletal muscles that control movement. "This lower efficacy is probably based on the fact that IGF-1 interferes with rather late events in the course of the disease, whereas mini-agrin tackles the structural deficits that are the primary cause of the muscular dystrophy." (PMID 22943509, 2012). "Recent examples include the use of mini-agrin and laminin-nidogen hybrid constructs to significantly delay muscular dystrophy in a mouse model." (PMID 40523614, 2025). "On the other hand, our findings align with the notion that Agrin expression diminishes in dystrophic muscles, corroborated by reduced Agrin expression observed in various mouse models of muscular dystrophy." (PMID 38461287, 2024). "Similarly, a muscle-agrin (y0z0) derived construct, termed mini-agrin, is worthy of mention for its potential in alleviating certain types muscular dystrophies." (PMID 31998752, 2019). "However, we did not observe any defects in agrin's level, molecular size, or its capacity to bind α‐dystroglycan in our patient muscles, strongly suggesting that impaired agrin glycosylation cannot explain the muscular dystrophy in our patients." (PMID 27807076, 2016). "Investigating the impact of Agrin on muscle SCs in mouse models of CMD and other forms of muscular dystrophy would be of significant interest." (PMID 38461287, 2024). "Potential therapeutic interventions including splice modulation, upregulation of the LAMA1 gene, mini-agrin and αLNNd are in development for LAMA2-related muscular dystrophy." (PMID 34281576, 2021).
spinal muscular atrophy (8 papers, 2018 to 2023). A motor neuron disease that affect the muscles, and characterized by muscle weakness and atrophy resulting from progressive degeneration and irreversible loss of the anterior horn cells in the spinal cord (i.e., lower motor neurons) and the brain stem nuclei. "Replacement of agrin through the expression of a motor neuron-specific transgene has also proven effective in mice with spinal muscular atrophy by increasing NMJ area and reducing intermediate filament accumulation." (PMID 29462312, 2018). "In addition, treatment of a mouse model of spinal muscular atrophy (SMA) with a soluble fragment of the synaptic organiser protein agrin, lead to improved motor performance and increased life span." (PMID 36869887, 2023). "Furthermore, administration of a stabilized form (NT-1654) of the C-terminal 44 kDa fragment of motor neuron-derived agrin, a MuSK activator, enhances NMJ formation and improves motor behavior and survival of a mouse model of spinal muscular atrophy." (PMID 32758427, 2020).
lung carcinoma (7 papers, 2021 to 2025). "The agrin protein, identified in the plasma of lung cancer animal models, has been associated with NSCLC progression through its activation of the phosphatidylinositol 3-kinase/Protein B kinase (PI3K/AKT) signaling pathway." (PMID 40584122, 2025). "This agrin‐EGFR‐integrin‐YAP/TAZ‐agrin positive cycle may be of great relevance for the stiff lung cancer matrix in patients harboring EGFR mutations." (PMID 40165020, 2025). "In lung cancer, Src/Akt pathway can promote the invasion and metastasis of lung cancer cells, suggesting that Src kinase may be an important factor for Agrin in regulating PI3K/AKT signal and causing tumor development." (PMID 35111682, 2021). "Here it is shown that EGFR dictates tumorigenic agrin expression in lung cancer cell lines, genetically engineered EGFR‐driven mouse models, and human specimens." (PMID 40165020, 2025). "Targeting this oncogenic loop through combinatorial treatments inhibits lung cancer due to agrin impairment." (PMID 40165020, 2025). "Lastly, we examined 20 human lung cancer patient‐derived xenografts (PDXs) for agrin, EGFR, and YAP expression." (PMID 40165020, 2025). "The highest-ranked genes in both cohorts of primary lung cancers and LC-BrMs included CCNL2, DVL1, ATAD3A, AGRN, and ISG15, where mutation patterns were clustered for the patients." (PMID 39593114, 2024). "Moreover, the combination therapy robustly expelled YAP/TAZ outside the nucleus thereby impacting its association with TEAD transcription, illustrating the importance of agrin–EGFR feedback in potentiating nuclear YAP/TAZ in lung cancers." (PMID 40165020, 2025). "Therefore, targeting the agrin‐EGFR‐YAP rigidity sensing module presents a promising therapeutic strategy for EGFR‐driven lung cancers." (PMID 40165020, 2025). "We, therefore, first tested whether agrin bestows stiffness‐dependent oncogenic potential in EGFR‐responsive lung cancer cell lines." (PMID 40165020, 2025). "Overall, these findings highlight a mutual dependency between agrin and EGFR in YAP activation in lung cancer cell lines." (PMID 40165020, 2025). "Together, the combined inhibition of EGFR–YAP/TEAD may offer a strategy to reduce lung tumorigenesis by disrupting agrin‐EGFR mechanotransduction, uncovering a therapeutic vulnerability for EGFR‐addicted lung cancers." (PMID 40165020, 2025).
amyotrophic lateral sclerosis (6 papers, 2016 to 2023). Amyotrophic lateral sclerosis (ALS) is a neurodegenerative disease characterized by progressive muscular paralysis reflecting degeneration of motor neurons in the primary motor cortex, corticospinal tracts, brainstem and spinal cord. "Lrp4 and Agrin antibodies have also been detected in patients with amyotrophic lateral sclerosis (ALS), and their pathogenic role in MG and ALS is unclear." (PMID 31269763, 2019). "In previous studies, the sera of nine (out of 65) Amyotrophic Lateral Sclerosis patients were agrin antibody positive." (PMID 34956185, 2021). "We also show that myofibers with dynein impairment or from an amyotrophic lateral sclerosis (ALS) model (SOD1G93A) show similar defects in myofiber formation and agrin-induced AChR clustering suggesting a role for dynein impairment in ALS progression." (PMID 27283349, 2016).
colorectal cancer (6 papers, 2018 to 2025). A primary or metastatic malignant neoplasm that affects the colon or rectum. "This is the first research to detail the possible underlying mechanism of BMs in colorectal cancer and identify the key pathogenic gene—AGRN." (PMID 39183444, 2024). "Moreover, an examination of genes linked to glycolysis has shown that IER3 and AGRN are significantly overexpressed in colorectal cancer and correlate with lower survival rates among patients." (PMID 41311582, 2025). "Matrine has been found to impede the advancement of colorectal cancer by modulating the AGRN/Wnt/β‐catenin pathway." (PMID 39183444, 2024). "Of note, they observed also that matrine, an alkaloid found in plants, has anti-tumor effects on colorectal cancer cells by inactivating the Wnt/β-catenin pathway via regulating AGRN expression." (PMID 37686696, 2023). "Matrine impedes the advancement of colorectal cancer by modulating the AGRN/Wnt/β‐catenin pathway." (PMID 39183444, 2024). "Concerning new findings not yet clearly linked to HNSCC, some authors found that AGRN downregulation reduces cell proliferation, migration, invasion, and enhances apoptosis in colorectal cancer cells." (PMID 37686696, 2023). "An immunoscreening of the extracellular proteome of colorectal cancer cells identified AGRN as an antigen that may be recognized by autoantibodies that exist in sera from colorectal cancer patients." (PMID 29552294, 2018). "AGRN and DAG1 have also been reported to be involved in ECM-receptor interactions in colorectal cancer." (PMID 40538442, 2025). "An examination of genetic information from patients with colorectal cancer disclosed that IER3 and AGRN, which play essential roles in the glycolytic pathway, are notably upregulated in colorectal cancer and are linked to reduced survival rates among patients." (PMID 41311582, 2025). "As for AGRN and THBS3, we have not found evidence on their role in colorectal cancer pathogenesis." (PMID 34938324, 2021).
lung adenocarcinoma (6 papers, 2019 to 2025). A carcinoma that arises from the lung and is characterized by the presence of malignant glandular epithelial cells. "A retrospective study of 120 lung adenocarcinoma patients provided robust clinical evidence that high AGRN expression correlates with a greater susceptibility to lymph node metastases and a poorer prognosis." (PMID 41340014, 2025). "The study identifies agrin‐EGFR mechanotransduction as a critical driver of lung adenocarcinoma which enhances EGFR signaling through an integrin‐FAK‐actomyosin dependent positive feedback on YAP/TAZ ‐TEAD in response to matrix stiffness." (PMID 40165020, 2025). "A previous study employing both single‐cell RNA sequencing and immunohistochemistry has demonstrated that AGRN is primarily expressed and secreted in lung adenocarcinoma cells." (PMID 41340014, 2025). "With the increasing risk score of patients with lymph node metastasis of lung adenocarcinoma, the expression of high-risk mRNAs (HMMR, B4GALT1, ANGPTL4, EXT1, GPC1, RBCK1, SOD1, AGRN) was obviously upregulated." (PMID 31847905, 2019). "In the reverse MR analyses, AGRN and IL12RB2 demonstrated potential reverse causal effects, suggesting that genetic liability to lung adenocarcinoma and small cell carcinoma, respectively, may influence circulating levels of these proteins." (PMID 41340014, 2025). "Additionally, an mRNA‐mining study identified AGRN as an independent indicator of poor prognosis and metastasis in lung adenocarcinoma." (PMID 41340014, 2025). "Additionally, adenovirus expressing Cre‐recombinase that led to the expression of EGFR‐L858R/T790 M in mouse lungs formed spatially diffused lung adenocarcinoma with increased agrin expression." (PMID 40165020, 2025). "AGRN's ability to enhance lung adenocarcinoma progression by activating the Notch signalling pathway and promote the tumorigenic phenotype of thyroid cancer cells, as well as its association with immune infiltration in thyroid tumours, underscores its significance in cancer biology." (PMID 39183444, 2024). "Agrin was highly expressed in both lung adenocarcinoma and squamous cell carcinoma." (PMID 35111682, 2021). "For the significant proteins identified in the observational analyses, Agrin (AGRN), CD5 antigen‐like (CD5L), glucosamine‐6‐phosphate isomerase 1 (GNPDA1), integrin beta‐2 (ITGB2) and neuronal‐specific septin‐3 (SEPTIN3) remained associated with lung adenocarcinoma in the two‐sample MR analyses." (PMID 41340014, 2025). "The relative expression levels of AGRN and ITGB2 in lung adenocarcinoma samples were significantly different from those in normal tissues (p for Wilcoxon tests < 0.05)." (PMID 41340014, 2025). "In a spontaneous lung adenocarcinoma generated by the expression of the EGFR L858R in type II pneumocytes under the control of doxycycline (Dox), induction of EGFR activated agrin expression within the multifocal adenocarcinomas when compared with adjacent or non‐induced lung tissues." (PMID 40165020, 2025). "AGRN directly interacts with NOTCH1 and increases the release of Notch intracellular structural domain 1 (NICD1), leading to the activation of the Notch pathway, which promotes the proliferation, migration and invasion of lung adenocarcinoma cells." (PMID 41340014, 2025).
oral squamous cell carcinoma (6 papers, 2014 to 2025). "Here we examined the role of agrin—a member of this matrix—in progression of oral squamous cell carcinoma (OSCC)." (PMID 29872149, 2018). "Using real time quantitative PCR (qRT-PCR), we showed that agrin and perlecan are highly expressed in oral squamous cell carcinoma." (PMID 25506919, 2014). "Additionally, previous studies demonstrated that agrin silencing interfered with cancer cell motility, proliferation, invasion, colony formation, and tumor spheroid formation in oral squamous cell carcinoma, highlighting agrin’s pathological role in cancer progression." (PMID 39123447, 2024). "In oral squamous cell carcinoma (OSCC), elevated agrin levels are observed in both malignant and precancerous tissues." (PMID 40299352, 2025). "It has also been revealed that Agrin has high expression in Oral squamous cell carcinoma (OSCC), and Agrin siRNA knockdown promoted a decrease in OSCC cell migration." (PMID 30135409, 2018).